IL6 (interleukin 6)
Diseases named in the same sentence as IL6 in open-access papers (continued):
Sharing a sentence is not in itself a finding about the gene and the disease.
diabetes (continued). "Poor prognostic factors for improvement were older age, poor handgrip strength, weight loss, poor physical activity, hospitalizations, previous cancer or stroke, lung disease, lower cognitive function, diabetes, osteoarthritis, low albumin levels and high IL-6 levels." (PMID 33193369, 2020). "In order to determine the underlying mechanisms by which BAI-LZM inhibits renal fibrosis and decreases inflammation, the protein expression levels of NF-κB, p-NF-κB p65, IL-1β, IL-6 and mTOR in diabetic kidney tissues were assessed using IF, IHC and western blot analyses." (PMID 32398108, 2020). "Studies have shown that miR-146 expression in peripheral blood monocytes decreased significantly while TRAF-6 mRNA expression increased in patients with type 2 diabetes mellitus and miR-146 expression is negatively linked to TRAF-6 and NF-κB mRNA levels as well as circulating TNF-α and IL-6." (PMID 32337281, 2020). "Furthermore, increased IL-6 concentrations in the groups of patients with pain secondary to leprosy and diabetes were noted." (PMID 32038662, 2020). "Moreover, diabetes enhanced the expression of IL-17, which altered the composition of oral microbiota, reduced the secretion of IL-6 and RANKL and inhibited neutrophil recruitment and bone resorption." (PMID 32634783, 2020). "Remarkably, overexpression of hypothalamic PDK2 reversed the effects of Pdk2 KO on diabetes-induced Tnf-α, Il-1β, and Il-6 mRNA expression, food intake, blood glucose, and expression of Npy, Agrp, and Pomc in the diabetic hypothalamus at 3 weeks post-STZ injection." (PMID 33219201, 2020). "The cytokine interleukin-6 was regarded as an important role in the pathogenesis of diabetes." (PMID 32660472, 2020). "Furthermore, different studies have shown that increased levels of MPO, IL-6 and hs-CRP are significantly associated with an increased risk of diabetes." (PMID 32650465, 2020). "Diabetes mellitus and AFB1 intoxication-induced oxidative stress in this study were associated with increased production of proinflammatory cytokines, IL-1β, IL-6, and TNF-α leading to hepatorenal injuries and the elevation of activities and levels of their function biomarkers." (PMID 32104544, 2020). "Tocilizumab, a monoclonal antibody against IL-6 may have a role in patients with diabetes to control overexpressed IL-6." (PMID 32527756, 2020). "Interleukin-6 was correlated with C-reactive protein (p < 0.0001) and with the incidence of insulin-dependent diabetes mellitus (p = 0.036), arterial hypertension (p = 0.044), reduced left ventricular function (p = 0.003), and severe coronary calcification (p = 0.015)." (PMID 32685095, 2020). "Compared with the euglycemia group, the CD3+ cell counts and the CD4+/CD8+ ratio were decreased, whereas the levels of IL-6 were increased in the secondary hyperglycemia group and diabetes group, with the diversities in the diabetes group being especially more significant." (PMID 33062712, 2020). "Due to the fact that there are relatively few data on other inflammatory factors in the included original studies, our study only analyzed CRP, TNF-α, and IL-6; other inflammatory factors that affect and participate in the course of diabetes should be explored in future research." (PMID 33456672, 2020). "In patients with type 2 diabetes mellitus, local changes in the periodontiumare characterized by increased production of reactive oxygen species andproinflammatory cytokines (IL-1, IL-6, and TNFα), as glycation productsaccumulate and become engaged in vigorous interaction with receptors." (PMID 31993238, 2019). "After adjustment for age, gender, duration of diabetes, and BMI, multivariate analysis showed significant association of smoking (p=0.002) and HOMA-IR (p=0.003) with intraocular IL-6 levels, while intraocular VEGF and systemic Lp-A levels correlated significantly (p=0.032)." (PMID 31396410, 2019).
diabetes (continued). "As a result of NF-κB activation induced by diabetes, retinas from diabetic mice treated with vehicle showed a significant upregulation of several proinflammatory cytokines (mRNA and protein) such as IL-1β and IL-6." (PMID 30862093, 2019). "Studies in Wistar rats have shown that diabetes in adult animals leads to IL-6 overexpression in the hippocampus and, as our study indicates, maternal diabetes may exert a similar effect in the brains of offspring." (PMID 31197747, 2019). "In healthy population and in those with different chronic diseases like diabetes, atherosclerosis and polyarthritis, the higher concentrations of 25(OH)D have been correlated with lower status of inflammatory biomarkers including interleukin 6, CRP, and tumor necrosis factor alpha." (PMID 30791895, 2019). "Among individuals with peri-implantitis, those having diabetes show an overproduction of multiple peri-implant fluid pro-inflammatory cytokines; IL-1, IL-6, IL-8, TNF-alpha, chemokine receptors CCR5 and CXR3, where the severity of dysregulation appears to be worsen with poor diabetes control." (PMID 31275749, 2019). "When HOMA-IR and smoking status, as significant correlates, were incorporated into the multiple regression model, both were confirmed as independent and significant correlates of intraocular IL-6 levels, after adjustment for age, gender, duration of diabetes, and BMI." (PMID 31396410, 2019). "To assess whether CPT improves inflammatory responses in diabetes-induced hepatic inflammation, we assessed IL-6, IL-1β, and TNF-α amounts in serum." (PMID 31404259, 2019). "In addition, patients in the high IL-6 group had a higher rate of diabetes mellitus and higher levels of serum C-reactive protein than those in the low IL-6 group (P = 0.0266 and 0.0073, respectively)." (PMID 30611204, 2019). "Therefore, despite diminished IL‐6 responses, absolute levels remained higher in the diabetes group." (PMID 30666661, 2019). "In rodent diabetes models, the increase in IL-6 and TNFα is maintained up to 24 weeks of age." (PMID 29301251, 2018). "In the same study, significant correlations of overhydration with markers of nutritional and inflammatory status (lower serum albumin and higher interleukin-6 and tumor necrosis factor-α) were reported in addition to those with systolic blood pressure, cardiovascular diseases, and diabetes mellitus." (PMID 30894885, 2018). "In addition, our data confirmed that the pain behavior coincided with the expression changes of inflammatory cytokines (TNF-α, IL-1β, IL-6, and IL-10) in rats with diabetes induced by STZ." (PMID 29713362, 2018). "In present study we also found the level of pro-inflammatory cytokines IL-1β and IL-6 in chronic diabetic rats were elevated, which was consistent with the opinion that inflammatory cytokines are involved in the pathogenesis of diabetes-related cognitive dysfunction." (PMID 30042685, 2018). "IL-6 rs1800796 and HSPD1 rs2605039 had interactions with diabetes on breast cancer risk." (PMID 28591216, 2017). "Since AGE has been shown to induce various inflammatory responses in diabetes, we checked two representative cytokines IL-6 and tumor necrosis factor (TNF)-α, both of which are classically known to be associated with the pathogenesis of DR, in addition to IL-1β." (PMID 29170525, 2017). "In a multivariate analysis, metformin remained significantly associated with the calcification scores, independently of age, gender, previous cardiovascular disease, eGFR-MDRD, tobacco use, diabetes duration, neuropathy, retinopathy, HbA1c, serum IL-6, and insulin prescription." (PMID 28202017, 2017). "Furthermore, there was increased expression of NF-κBp65, a transcription factor and serum TNF-α and IL-6 levels in diabetes + IR group as compared to diabetic control group (P < 0.001)." (PMID 28181586, 2017).
diabetes (continued). "Studies have shown that visceral fat produced more angiotensin, interleukin-6 and plasminogen activator inhibitor than subcutaneous fat did, it had closer correlation with hypertension, diabetes, metabolic syndrome, and was more important than BMI as a cardiovascular risk." (PMID 28955229, 2017). "Diabetes mellitus, age ≧ 50 years, IL-18 ≧ 804.3 pg/ml, IL-6 ≧ 3.92 pg/ml, and IL-1ß ≧ 0.86 pg/ml." (PMID 28474577, 2017). "It is not clear if these data are readily applicable to chronic forms of hyperglycemia such as types 1 and 2 diabetes but an ongoing clinical trial with a monoclonal antibody against IL‐6 in type 1 diabetes (NCT02293837) may be informative." (PMID 27042306, 2016). "Besides reproducing our earlier data of LPS response on NETosis from diabetes individuals, we also observed varied effect of IL-6 under different glucose concentrations." (PMID 27811985, 2016). "Genotypic frequencies and association of the IL6-174 SNP with presence of plaques, increased IMT and degree of stenosis, in the irradiated and non-irradiated individuals (adjusted for gender, age, hypertension, diabetes, and smoking habits)." (PMID 27662210, 2016). "Interestingly, in IL-6 knockout mice the level of miR-29 in the heart further elevated than WT controls upon diabetes induction." (PMID 26972749, 2016). "Pro-inflammatory cytokines, TNF-α and IL-6, are produced during the inflammatory process and are principal stimulators of acute-phase proteins and other markers of chronic inflammation commonly detected in diabetes mellitus." (PMID 26888412, 2016). "Although cytokines have been associated with fatigue in those with cancer and diabetes, no studies were found that examined IL-6 as an explanatory factor for persistent fatigue after MI." (PMID 27148509, 2016). "Significant main effect of diabetes was found in IL6 (P = 0.006)." (PMID 27512375, 2016). "IL-6 secreted during the acute phase of inflammation has varied effects on cells in diabetes." (PMID 26861982, 2016). "Since IL-6 is produced by human mononuclear cells, this suggests that IL-6 might be a common link between leukocyte count and diabetes." (PMID 26891449, 2016). "In animal models of diabetes, histidine supplementation could reduce the levels of IL-6, TNF-α and CRP." (PMID 27409634, 2016). "Moreover, concomitant with suppression in Th17, immunoregulatory induced generation of Treg cells that are important in the control of diabetes with a concomitant increased level of IL-10 production and decreased in IL-6 and IFN-γ." (PMID 27165305, 2016). "Although we included a wide range of inflammatory markers in the adjustment there may exist other important inflammatory markers, such as interleukin-6 (IL-6) and C-reactive Protein (CRP), that may be associated with poor lung function and diabetes." (PMID 27165091, 2016). "We also found a strong correlation between IL-6 and homocysteine levels in diabetes." (PMID 27811985, 2016). "Previous studies have reported that various inflammation markers, e.g., interleukin-6, tumor necrosis factor α (TNFα) and CRP are associated with diabetes It is believed that TNFα contributes to diabetes through its interaction with insulin signaling pathways and beta-cell function." (PMID 26891449, 2016). "Indeed, previous studies suggested that the diabetes was an inflammatory disease, which was mainly based on the increased plasma concentrations of IL-6, IL-1, and TNF-α." (PMID 26944557, 2016). "Furthermore there is suggestive evidence on a potential link between epigenetic changes at inflammatory genes (including IL6) and diabetes." (PMID 26911440, 2016). "It is suggested that in the pathogenesis of PAD in patients suffering from diabetes, a significant role is played by pro-inflammatory cytokines and acute-phase proteins; the mentioned elements include interleukin-6 (IL-6), tumor necrosis factor (TNF)-alpha, C-reactive protein (CRP), and fibrinogen." (PMID 27834825, 2016).
diabetes (continued). "Previous studies have suggested that phospho-p38 MAPK expression is downregulated by resveratrol, which has been shown to ameliorate diabetes-induced cardiac dysfunction, interleukin-6 release in PC12 cells, and oxidized low-density lipoprotein-induced macrophage apoptosis." (PMID 26799794, 2016). "Carriers of the major G-allele of IL6 -174G > C also had significantly increased odds of diabetes, but interactions were statistically non-significant." (PMID 26911440, 2016). "Thus, EP4 was required for the effects of diabetes on Il6 and markedly suppressed the effects of diabetes on Tnfa levels in macrophages." (PMID 27351842, 2016). "But compared to IL–1, the role of IL–6 in the pathogenesis of diabetes is controversial." (PMID 26448147, 2015). "However, the increase of IL-6 in G2 as a result of STZ induced diabetes and its decrease with the concurrent treatment with Moringa suggests that Moringa has antidiabetic activity." (PMID 25629046, 2015). "In this study, IL-6 increased in parallel with the severity of the renal disease (albuminuria) and in multiple regression analysis albumin excretion rate, HDL-cholesterol and duration of diabetes were independently associated with IL-6." (PMID 26239462, 2015). "Additionally, levels of IL-17 and IL-6, which are known to induce Th17 differentiation, positively correlated with severity of diabetes." (PMID 26146464, 2015). "The serum levels of IL-6, which is directly associated with early glomerular structural abnormalities, have been shown to be substantially higher in type 2 diabetes mellitus (T2DM) patients with DN than in T2DM patients without renal disease." (PMID 26517838, 2015). "Considering the dual roles played by IL-6 on insulin sensitivity in diverse tissues and that these effects depend on different times of exposition and signaling pathways, further studies are necessary to ensure the safety of blocking IL-6 pathways as a pharmacological target to treat diabetes." (PMID 26578976, 2015). "To understand the mechanism underlying the effects of ASCs on CAIA, we examined the serum levels of five cytokines (IL-15, IL-1α, IL-6, IL-7, and TNFα), five diabetes-related hormones (resistin, GIP, GLP-1, ghrelin, and leptin), and adiponectin using multiplex immunoassays." (PMID 26210906, 2015). "Recent studies have proposed that IL-6 could be involved in insulin resistance and diabetes and its complications." (PMID 26153197, 2015). "Because TTP is known to regulate the expression of multiple cytokines via its ability to bind to AREs, the expression of TTP at an early stage of disease is consistent with the possibility that decreased TTP expression precedes and regulates increased IL-18 and IL-6 in diabetes." (PMID 26517838, 2015). "Downstream effects of IL-6 in a pro-inflammatory context include increased expression of adhesion molecules, plasminogen activator inhibitor-1, and release of chemokines, which are all known risk factors for hypertension, CVD, and diabetes." (PMID 25938443, 2015). "In other studies, circulating IL-6 as well as hs-CRP were inversely associated with parasympathetic nervous system tone measured as LF of HRV both, in healthy individuals and patients with CVD or diabetes." (PMID 25133672, 2014). "According to multivariate logic analyses, after adjustment for cardiovascular risk factors such as age, gender, SBP, BMI, smoking, diabetes duration, HbA1c, CRP, IL-6, LDL and medication, HIF-1α levels still significantly and independently predicted the presence of CAC." (PMID 24564828, 2014). "In addition, NR4A1 expression was shown to significantly correlate with the levels of the inflammatory cytokines, TNF-α and IL-6, as well as the diabetes-related parameters, FIN, FBG, HOMA-IR and FFA." (PMID 25289075, 2014).
diabetes (continued). "An additional important contribution of this study is that after adjusting for confounders including BMI, smoking status, race, gender, hypertension and diabetes, IL-6 and CRP, which are two key markers of chronic inflammation, showed association with oral health conditions." (PMID 23950871, 2013). "In addition, we also demonstrated here that inhibition of ERK1/2 by U0126 significantly ameliorates diabetes-induced upregulation of iNOS, IL6, and TNF-α in the retina." (PMID 23671886, 2013). "As a result of diabetes, inflammation increases and the release of cytokines like IL-6 increases." (PMID 24223616, 2013). "Thus, blocking type I IFN signaling during diabetes partially but significantly restored the levels of IL-1α, IL-1β, IL-6, and CXCL10." (PMID 23533683, 2013). "In the current study, we showed that plasma levels of TNF-alpha and IL-6 were remarkably elevated in diabetic rats at 4 weeks after the establishment of diabetes, and NAC treatment decreased them, indicating that NAC can inhibit the inflammation reaction in diabetes." (PMID 23853776, 2013). "Indeed, the results presented here demonstrate that blocking type I IFN signaling during diabetes partially yet significantly restored the levels of IL-1α, IL-1β, and IL-6." (PMID 23533683, 2013). "With regard to the inflammatory biomarkers, participants with incident diabetes had higher baseline levels of CRP, fibrinogen, interleukin-6, urinary isoprostanes, lipoprotein-associated phospholipase A2 mass, monocyte chemoattractant protein-1, P-selectin, and tumor necrosis factor receptor." (PMID 23130155, 2012). "However, IL-6 also reflects the low-grade chronic inflammatory state that characterizes diabetes per se, the increased level of insulin resistance, and the increase in visceral adipose tissue, all of them present in the metabolic syndrome." (PMID 22924123, 2012). "It has been suggested that diabetes-related oxidative stress may induce vascular IL-6 expression and activate IL-6R and gp130, which in turn activates the JAK2/STAT3 signaling cascade." (PMID 22553973, 2012). "Insulin resistance syndrome and type 2 diabetes mellitus are considered as an inflammatory state due to increased production of pro-inflammatory cytokines, such as TNFα and IL-6; b) motility impairment has been described in diabetic patients showing delayed duodenum-cecal transit time." (PMID 23166628, 2012). "Our study suggests that autonomic dysfunction is seen early in the course of diabetes, and that this occurs alongside alterations in various adipokines, including adiponectin and leptin, and various inflammatory adipocytokines, including IL-6." (PMID 22110481, 2012). "IL-6 correlated negatively with sdNN, suggesting an association between IL-6 and abnormalities in both the sympathetic and parasympathetic components of the reduced HRV seen in patients with diabetes." (PMID 22110481, 2012). "In this study, both plasma TNF-α and IL-6 levels were significantly increased in rats with diabetes, which may contribute to the decreased plasma APN level in diabetes." (PMID 21912612, 2011). "One hypothesis for the increased disease prevalence in these communities is underlying chronic inflammation (elevated CRP or IL-6), a known component and predictor of CVD and diabetes, that is linked to a diverse range of pathologies." (PMID 21818333, 2011). "It would be expected, as a consequence of increased telomere attrition, that this group would have more senescent cells present and thus higher IL-6 levels and have an elevated risk of a range of conditions, if indeed IL-6 is causally related to CVD and diabetes." (PMID 21818333, 2011). "The negative associations seen in nonobese individuals could also be the result of an anti-inflammatory effect of diabetes medications in a population with generally lower adipose-generated levels of IL-6 and lower CRP." (PMID 20123638, 2010).